TPRX2 (tetrapeptide repeat homeobox 2)
Description:
Transcription factor expressed after fertilization required for zygotic genome activation (ZGA), a critical event in early embryonic development during which the developmental control passes from maternally provided mRNAs to the expression of the zygotic genome after fertilization. Binds and activates expression of key ZGA marker genes, such as NANOGNB, ZSCAN4, DUXB, KLF5 and DPPA3. Binds to regulatory DNA sequences containing a 5'-TAATCC-3' sequence motif.
Synonyms: TPRX2P1; TPRX2P; TPRXP1
Tractability: No criterion of Open Targets' tractability assessment is met for any kind of drug.
Gene: Protein-coding gene on chromosome 19 (47,859,235 to 47,861,721, forward strand). Ensembl gene ENSG00000259009.
Subcellular location: Nucleus
Pathways (Reactome):
Developmental Biology: Zygotic genome activation (ZGA)
Gene Ontology:
Molecular function: DNA-binding transcription factor activity, RNA polymerase II-specific; RNA polymerase II cis-regulatory region sequence-specific DNA binding; DNA binding
Biological process: maternal-to-zygotic transition of gene expression; regulation of transcription by RNA polymerase II; regulation of DNA-templated transcription
Cellular component: nucleoplasm; nucleus
Homologues: Orthologues: chimpanzee TPRX2 (95% identical). Paralogues in human: TPRX1 (74% identical).